GOLGA8EP (golgin A8 family member E, pseudogene)
Synonyms: formerly GOLGA8E
Gene: Transcribed unprocessed pseudogene on chromosome 15 (22,427,634 to 22,437,902, reverse strand). Ensembl gene ENSG00000185182.
Diseases named in the same sentence as GOLGA8EP in open-access papers:
GOLGA8EP is named in the same sentence as 1 disease in open-access papers, as found by Europe PMC text mining. Sharing a sentence is not in itself a finding about the gene and the disease.
GOLGA8EP shares sentences with these, for which no sentence is quoted: autoimmune (1 paper).